MTOR (mechanistic target of rapamycin kinase)
Diseases named in the same sentence as MTOR in open-access papers (continued):
Sharing a sentence is not in itself a finding about the gene and the disease.
glioma (continued). "Imipramine stimulated autophagy progression in human U-87MG glioma cells, while ketamine promotes neural differentiation of mouse embryonic stem cells via mTOR activation." (PMID 35222638, 2022). "EVs derived from M2 Mφs were also reported to have a therapeutic effect in a rat knee osteoarthritic model or in glioma through inhibition of the PI3K/mTOR signalling pathway." (PMID 36229897, 2022). "Resveratrol downregulated the PI3K/Akt/mTOR signaling pathway, which resulted in apoptosis in glioma cells." (PMID 36500361, 2022). "The high RIOK3 level in glioma promotes the proliferation, migration, and invasion of glioma cells through the AKT/mTOR pathway." (PMID 35281872, 2022). "and others have further shown that the PI3K/AKT/mTOR pathway controls glioma stem cell proliferation, invasion, angiogenesis, and metastases." (PMID 35392088, 2022). "On the one hand, autophagy induced by nutrient starvation or by inhibition of mTOR impairs EMT for glioma cells." (PMID 36338770, 2022). "In glioma, activation of AKT/FOXO3a and AKT/mTOR signaling pathways mediates the promotion of miR-1908-5p on the malignant phenotype of glioma cells U87." (PMID 35463352, 2022). "Meanwhile silencing of UBE2C in glioma leads to significant inhibition of the PI3K-Akt-mTOR pathway, while avoiding autophagy." (PMID 36291283, 2022). "Mimicking the conditions of the glioma microenvironment by subjecting the cells to hypoxia and nutrient deprivation, we found that mTOR and autophagy inhibition, either alone or in combination, protect glioma cells from hypoxia-induced cell death." (PMID 36202792, 2022). "To investigate the signaling pathway involved in the regulatory mechanism of CAMK1D in glioma, we predicted and determined that the PI3K/AKT/mTOR pathway was critically involved in the inhibitory effect of CAMK1D in glioma." (PMID 35494053, 2022). "The researchers further demonstrated that silencing of TRAM2 blocked the malignant progression of glioma by inhibiting the PI3K/Akt/mTOR signaling, rendering it a pathway with therapeutic potential." (PMID 36425564, 2022). "Recently, a new KI, PI-103, which inhibits both PI3K- α (a main isoform driving malignant progression in glioma) and mTOR signaling, was used in several preclinical glioma models." (PMID 36555334, 2022). "miR-92a overexpression promotes glioma cell proliferation through the KLF4 (Kruppel-like factor 4)/AKT/mTOR signaling pathway." (PMID 36479040, 2022). "We have previously reported that mTOR inhibition protects glioma cells from hypoxia-induced cell death partly through global inhibition of cellular growth and metabolism, which, in turn, helps cells to economize energy resources." (PMID 36202792, 2022). "It was reported that miR-372-downregulated PHLPP2 markedly inhibited cell proliferation while suppressing glioma tumor growth in xenograft mouse model by increasing the phosphorylation levels of Akt and mTOR." (PMID 35654777, 2022). "In order to understand the pathway by which curzerene inhibits cell proliferation, we used Western blotting to detect the levels of activation of molecules in the mTOR pathway in the glioma cell lines." (PMID 35048517, 2022). "In the context of hypoxia and starvation, autophagy was strongly induced in glioma cells and further increased by mTOR inhibition." (PMID 36202792, 2022). "LINC00470 in GBM- exosome can bind to miR-580-3p in glioma cells and stimulate the PI3K/AKT/mTOR pathway, impeding autophagy and promoting glioma cell proliferation." (PMID 37305396, 2021). "There are also suggestions that simultaneous inhibition of the expression of PI3K or Akt with mTOR is more effective in the elimination of glioma cells via programmed death than a single kinase of the pathway." (PMID 34068110, 2021). "Further, the expression of drug-resistance protein ABCG2, autophagy related proteins, and PI3K/Akt/mTOR pathway were measured by western blot or qRT-PCR in TMZ-treated glioma cells." (PMID 34454479, 2021).
glioma (continued). "For example, lncRNA CASC2 negatively regulates miR-21 to suppress cell growth of glioma, whereas lncRNA CRNDE promotes glioma cell growth and invasion through mTOR signaling." (PMID 34194477, 2021). "Recent findings suggest that VPA enhances apoptosis by promoting autophagy with the decrease in AKT/mTOR phosphorylation in gliomas." (PMID 34685502, 2021). "Everolimus (an mTOR inhibitor) has also been recently tested in a phase II clinical trial for treatment of low grade gliomas in patients with NF1 (NCT01158651); however, the results of this clinical trial have not been published yet." (PMID 34359780, 2021). "Studies have shown that PI3K/AKT/mTOR signaling pathway is closely related to the regulatory mechanism of glioma." (PMID 33676540, 2021). "Targeting glutamine metabolism with JHU-083 showed efficacy in preclinical models of IDHmut glioma and measurably decreased mTOR signaling." (PMID 33681764, 2021). "Pharmacological targeting of the PI3K/mTOR pathway by specific inhibitors in human nasopharyngeal, colorectal, and glioma cells was effective in diminishing tumor hypoxia by reducing mitochondrial oxygen consumption." (PMID 34199959, 2021). "Autophagy: H19 overexpression suppressed autophagy of glioma cells via regulating the mammalian target of rapamycin (mTOR)/Unc-51 like autophagy activating kinase 1 (ULK1) axis by inducing increased ULK1 phosphorylation and inhibiting mTOR phosphorylation." (PMID 34322395, 2021). "CASC2 is downregulated in glioma cells and thus increases autophagy through the mTOR signaling pathways." (PMID 33525678, 2021). "Our study also showed that using sempervirine in combination with Akt inhibitor (MK) or mTOR inhibitor (RA), the survival rate of glioma U251 cells was lower than when they were treated with sempervirine alone." (PMID 34916946, 2021). "This lncRNA negatively regulates miR-136-5p by binding as a ceRNA, thereby inhibiting Bcl-2 and Wnt2, which act downstream of the PI3K/Akt/mTOR signaling pathway, thus enhancing the glioma malignancy." (PMID 33980320, 2021). "Taken together, the research results in this paper indicated that the exosomes miR-15a and miR-92a derived from M2 macrophages inhibit the migration and invasion of glioma cells through the PI3K/AKT/mTOR signaling pathway." (PMID 33676540, 2021). "YAP also seems to closely interact with the PI3K/AKT/mTOR (Phosphatidylinositol 3-kinase/AKT serine/threonine kinase/Mechanistic target of rapamycin kinase) signaling pathway in glioma." (PMID 33477668, 2021). "TSN significantly inhibited the phosphorylation of PI3K, Akt, and mTOR proteins in glioma cells; furthermore, changes in the levels of expression of MMP proteins, cell-cycle-related proteins, and apoptotic proteins were observed." (PMID 34530814, 2021). "The modulation of crucial downstream molecular targets (e.g., Akt and mTOR) of this axis plays a vital role in preventing glioma progression." (PMID 34439380, 2021). "The expressions of active Akt/mTOR form were lessened due to the glioma cell exposure with fucoxanthin or PI3K inhibitor, LY294002, individually." (PMID 34440090, 2021). "In conclusion, decorin suppresses invasion and EMT phenotype of glioma by inducing autophagy via c-Met/Akt/mTOR axis." (PMID 34386415, 2021). "Down-regulation of RIOK3 significantly reduced the AKT/mTOR signaling pathway activity and induced apoptosis of glioma cells." (PMID 34138931, 2021). "Two recently published studies report that, in glioma, up-regulation of KIF3C is associated with patients’ unfavorable prognosis; functionally, KIF3C can regulate the PI3K/AKT/mTOR signal pathway to inhibit glioma cell growth." (PMID 34193018, 2021). "Collectively, these results demonstrated TSN inhibited glioma tumor progression by targeting PI3K/AkT/mTOR signaling pathways in vivo." (PMID 34530814, 2021). "BRCA1-associated proteins inhibit glioma cell proliferation and migration through the TGF-AKT/PI3K/mTOR signaling pathway." (PMID 33676540, 2021).
glioma (continued). "The Akt/mTOR signaling pathway regulates cell proliferation and self-renewal, promoting glioma proliferation." (PMID 34108621, 2021). "Our results indicate that inhibition of the PI3K/Akt/mTOR pathway sensitizes glioma cells to apoptosis upon temozolomide treatment, which was correlated with ER stress." (PMID 34068110, 2021). "Sempervirine induced G2/M phase arrest in glioma cells and initiated apoptosis and autophagy by regulating the Akt/mTOR signaling pathway." (PMID 34916946, 2021). "Mechanistically, PRELID1P6 inhibits the ubiquitin-mediated degradation of hnRNPH1, thus promoting glioma cell proliferation by the Akt/mTOR signaling pathway." (PMID 34108621, 2021). "Treatment of glioma activated microglial cells with mTOR blockers promoted M2 differentiation to cytotoxic M1 phenotype, as evidenced by decreased Arg-1 and IL-10 gene expression." (PMID 34439380, 2021). "RIOK3 can also promote the proliferation, invasion and migration of glioma cells through protein kinase B/mammalian target of rapamycin (AKT/mTOR) signaling pathway." (PMID 34475988, 2021). "Collectively, these findings indicate that M2 macrophage-derived exosomal miR-15a and miR-92a inhibit cell migration and invasion of glioma cells through PI3K/AKT/mTOR signaling pathway." (PMID 33676540, 2021). "MEG3 induces autophagy by upregulation of sirtuin 7 and inhibition on the PI3K/AKT/mTOR pathway in glioma cells." (PMID 33602903, 2021). "Collectively, we summarized that the knockdown of PRELID1P6 inhibited glioma progression via the hnHNPH1-Akt/mTOR pathway axis." (PMID 34108621, 2021). "mTOR has been the target of several preclinical studies, including experiments using subcutaneous glioma models in which dual inhibition of both PI3K and mTOR was tested." (PMID 34462635, 2021). "In our hands, this evidence has been also confirmed showing that not only mTOR inhibitors but also generic treatments able to increase intracellular ROS can overcome resistance to TMZ in glioma cells by inducing CMA activity." (PMID 33672324, 2021). "Because hnRNPH1 is vital for PRELID1P6-promoted glioma proliferation, we also detected the phosphorylation levels of Akt/mTOR signaling pathway proteins after hnRNPH1 knockdown." (PMID 34108621, 2021). "It was further figured out that expression of phosphorylation in Akt and mTOR was dramatically decreased by fucoxanthin treatment of the glioma cells in concentration of 25 and 50 μM." (PMID 34440090, 2021). "What’s more, ibrutinib is a promising therapeutic strategy for glioma, blocking the glioma cell proliferation, migration, and invasion properties and inducing glioma cell apoptosis and autophagy, targeting the Akt/mTOR pathway." (PMID 34784299, 2021). "in xenograft glioma mouse models show that presynaptic and postsynaptic function is disrupted in the presence of glioma with microenvironmental neurolignin 3 (NLGN3) being hijacked to induce signaling through the PI3K/PTEN/AKT/mTOR pathway." (PMID 34532286, 2021). "The present study shows that BCA treatment obviously inhibits the expression of p-Akt and p-mTOR in glioma cells by Western blot detecting." (PMID 34307130, 2021). "As an example, hydrogen peroxide, through the activation of BNIP3, inhibits mammalian target of rapamycin (mTOR) activity and induces autophagy in C6 glioma cells after sanguinarine treatment." (PMID 33920160, 2021). "The RTK/PI3K/Akt/mTOR signaling pathway is a crucial player in the genesis and progression of gliomas." (PMID 34063168, 2021). "Along with a reduction in p-RPS6, combined application of MNK1/2 inhibitor and mTOR inhibitor has shown synergism against glioma growth." (PMID 33564073, 2021). "Inhibiting autophagy-related apoptosis by Cathepsin S has been proven as an effective therapeutic strategy for glioma through inhibition of PI3K/AKT/mTOR/p70S6K signaling pathway and activation of JNK signaling pathway." (PMID 33663509, 2021).
glioma (continued). "Downregulated miR target genes showed pathway enrichments in axon guidance, long-term potentiation, glioma, non-small lung cancer, and mTOR signaling pathway." (PMID 34775883, 2021). "For example, curcumin is a widely recognized as a TCM inducer of autophagy‐dependent death, which was reported to inhibit gliomas in vitro and in vivo via Akt/mTOR/P70S6K pathway and ERK1/2 pathway." (PMID 34632655, 2021). "In our further study, the silencing of CRNDE contributed to the induced autophagy in glioma cells through upregulation of the PI3K/Akt/mTOR pathway, accompanied by the suppression of cell viability, proliferation, and apoptosis under treatment with TMZ." (PMID 34454479, 2021). "Higher AKT and mTOR hyperphosphorylation (activation) has been reported in high-grade gliomas (Grade III and IV) as compared to low-grade ones (Grade I and II)." (PMID 33525678, 2021). "LINC00470 in GBM-exo can bind to miR-580-3p in glioma cells to regulate WEE1 expression and activate the PI3K/AKT/mTOR pathway, thereby inhibiting autophagy and enhancing the proliferation of glioma cells." (PMID 33663509, 2021). "One important relationship between the nuclear factor Nrf2 (NFE2L2) and mTOR has been pointed out to explain the complex role of ROS in gliomas." (PMID 33540681, 2021). "More specifically, we identified LINC00470 can bind to miR-580-3p to regulate WEE1 and thereby regulate PI3K/AKT/mTOR pathway, ultimately mediating cell autophagy in glioma." (PMID 33663509, 2021). "Glioma growth and proliferation is regulated by the mTOR pathway together with eukaryotic initiation factors (eIFs)." (PMID 33807050, 2021). "It was previously reported that HULC (highly upregulated in liver cancer) lncRNA promotes proliferation, invasion, and angiogenesis by regulating the PI3K/AKT/mTOR axis in glioma." (PMID 33668685, 2021). "Honokiol specifically inhibits PI3K/mTOR signaling activation in gliomas, promotes the elimination of GSCs, and reverses TMZ resistance using GBM8401 SP cells, which appear to have higher expression of MGMT and to be more resistant to TMZ." (PMID 33762015, 2021). "p-AKT and p-mTOR were reported to be activated or over-expressed in human gliomas, and the labeling index of the PI3K/AKT/mTOR pathway increased with increasing grade of malignancy." (PMID 33676540, 2021). "In glioma cells, a high TGFBI expression was associated with poor prognosis and phosphorylation of AKT and mTOR." (PMID 33921897, 2021). "JHU-083 reduced glioma cell growth in vitro, modulated cell metabolism, and disrupted mTOR signaling and downregulated Cyclin D1 protein expression, through a mechanism independent of TSC2 modulation and glutaminolysis." (PMID 33681764, 2021). "The limited effects of pan-PI3K inhibitors and rapamycin analogs in the clinic provide a rationale for trials with drugs targeting both PI3K and mTOR for glioma treatment." (PMID 32116702, 2020). "Western blotting showed that DMC-BH significantly decreased p-Akt and p-mTOR expression in orthotopic glioma tissues." (PMID 33221748, 2020). "MicroRNAs miR-130a-3p, miR-484 and miR-99a were enriched in the glioma (hsa05214) and mammalian target of rapamycin (mTOR) signalling pathway (hsa04150)." (PMID 33023154, 2020). "In conclusion, our data indicated that ARG mediated autophagy by targeting the AKT/mTOR pathway and inhibited the malignant behavior of glioma cells." (PMID 33015162, 2020). "Taken together, these findings demonstrated that JMJD2A epigenetically regulated the expression of PDK1 to activate Akt-mTOR signaling and promote glioma cell proliferation." (PMID 32256210, 2020). "Upstream of it was the PI3K/AKT pathway regulating mTOR activity; therefore, the results indicated that ARG inhibited the growth of glioma by triggering autophagy through the AKT/mTOR pathway." (PMID 33015162, 2020).
glioma (continued). "Mechanistically, LINC00998 prevented CBX3 ubiquitination and promoted tri-methylation of histone H3K9 in c-Met promoter region, further downregulated the c-Met/Akt/mTOR signaling pathway, and then attenuated glioma progression." (PMID 33268783, 2020). "The connection between glutaminolysis and glycolysis, their dependence on cellular mTOR activity were deeply investigated in many previous glioma studies." (PMID 31187466, 2020). "Small molecule inhibitors of Akt-mTOR cascade have exhibited favorable preclinical results and entered clinical trials for human glioma." (PMID 33159013, 2020). "Due to epidermal growth factor receptor (EGFR) amplification, PTEN depletion and possible other mutations, overactivation of PI3K-Akt-mammalian target of rapamycin (mTOR) cascade is commonly detected in human glioma." (PMID 33159013, 2020). "Such an inhibitory effect of YTX on mTOR pathway activity was until now only described for human glioma cells exposed to much higher concentrations of 34 and 286 μg·L−1." (PMID 31936833, 2020). "RIOL3 promoted the proliferation and survival of gliomas through the AKT/mTOR signaling pathway In our study, we identified the phosphorylation of AKT and mTOR inactivated in ARG-treated glioma cells." (PMID 33015162, 2020). "All these results indicate that miR-450a-5p exhibits a negative correlation with the EGFR, and regulates the EGFR-induced PI3K/AKT/mTOR signaling pathway in glioma cells." (PMID 32820249, 2020). "Although the role of miR-199a-3p in glioma progression was previously investigated, the ischemic injury mechanism of peritumoral neurons, involving miR-199a-3p, exosomes, and the mTOR signaling pathway, has rarely been studied." (PMID 33110474, 2020). "JMJD2A activated Akt-mTOR signaling pathway and regulated protein synthesis in glioma cells via promoting PDK1 expression." (PMID 32256210, 2020). "Recent reports have identified mixed transcriptional states in the TAM population in glioma patients, and here, we identify mTOR signalling as a key driver of this intratumoral TAM heterogeneity." (PMID 32567735, 2020). "HULC silencing suppressed angiogenesis by regulating ESM-1 via the PI3K/Akt/mTOR signaling pathway in human gliomas." (PMID 32010942, 2020). "We showed that JMJD2A promoted protein synthesis by activating the Akt-mTOR pathway in pediatric high-grade gliomas tissues and glioma cell lines." (PMID 32256210, 2020). "The PI3K pathway is one of the most altered pathways in IDH-wildtype gliomas, in consequence of PI3K kinase mutations, loss of PTEN suppressor functions, or activated mTOR and resulted in poor prognosis as shown by previous researches." (PMID 33747896, 2020). "Subsequently, the mechanism by which celastrol disrupted VM formation was investigated and the results demonstrated that suppression of the PI3K/Akt/mTOR signaling pathway disrupts VM formation in glioma cells." (PMID 32116702, 2020). "The neoplastic transformation of gliomas is associated with excessive activation of the Ras/Raf/MEK/ERK and PI3K/Akt/mTOR pathways." (PMID 33171577, 2020). "The current study indicates that celastrol inhibits the growth, angiogenesis, and VM formation of glioma through a mechanism likely related to suppression of the PI3K/Akt/mTOR pathway." (PMID 32116702, 2020). "Based on this result and on our previous data, the effects of mTOR inhibition seem to converge to counter-act the in vitro glioma proliferation, migration and invasion." (PMID 32823532, 2020). "Because DMC-BH is a DMC derivative, we further investigated the inhibitory effects of DMC-BH on gliomas by targeting the Akt/mTOR signaling pathway." (PMID 33221748, 2020). "Synergy studies with the commercially-available selective pan-PI3K inhibitor GDC0941 provided evidence of the synergistic effect of concurrently inhibiting mTOR and PI3Ks in glioma cell growth." (PMID 31787462, 2020).